AKT1 (AKT serine/threonine kinase 1)
Diseases named in the same sentence as AKT1 in open-access papers (continued):
Sharing a sentence is not in itself a finding about the gene and the disease.
glioblastoma (353 papers, 2009 to 2026). The most malignant astrocytic tumor (WHO grade IV). "These bioinformatics and computational analyses suggest that vortioxetine suppresses glioblastoma development by modulating the functions and activities of AKT1, HIF1A, CDH1, NFKB1, and associated signaling pathways, such as the Rap1, chemical carcinogenesis-ROS, and HIF-1 signaling pathways." (PMID 40312983, 2025). "Similarly, cyclo(L-Pro-L-Phe) isolated from Bacillus species also caused apoptosis in U-87MG cells from human glioblastoma through AKT1 inactivation by down-regulating the phosphorylation of AKT1 serine/theorine kinase at 0.01 mg/mL." (PMID 30760201, 2019). "Finally, we linked IRE1α and AKT1 activity to SPARC production: PTEN-negative glioblastoma cells with high p-AKT1 levels produced SPARC when IRE1α was inactivated with the inhibitor 4μ8C." (PMID 31062076, 2019). "Furthermore, increased AKT3 mRNA levels were associated with increased patient survival and lower grade glioblastomas suggesting a more favourable outcome for these patients, whereas AKT1 and AKT2 expression was increased in higher grade tumours." (PMID 28082369, 2017). "The results confirmed that HSP90α and AKT1 were the molecular targets of sciadopitysin in inhibiting glioblastoma." (PMID 38911393, 2024). "Based on the key module, HSP90AA1 and AKT1 were selected as the key genes of sciadopitysin targets in glioblastoma." (PMID 38911393, 2024). "A previous report has revealed that DDR1 interacts with the 14-3-3/Beclin1/Akt1 protein complex and regulates autophagy-mediated therapy sensitivity in glioblastoma through phosphorylation of the tyrosine 513 site." (PMID 38071340, 2023). "Immunoprecipitation experiments showed that both TRAF4 and SETDB1 interacted with AKT1 in glioblastoma cells." (PMID 36077559, 2022). "KAT2B-mediated AKT1acetylation is able to enhance phosphorylation with AKT1 at threonine and serine sites, and further promotes glioblastoma cells proliferation." (PMID 34130593, 2021). "This AKT inhibitor was chosen because it directly inhibits AKT1/2/3 phosphorylation at S473 and showed efficacy in glioblastoma." (PMID 34681618, 2021). "This suggests that up-regulation of miR-4731, which results in EGFR, ERK-1,2 and AKT-1,2 suppresion, decrease the proliferation of glioblastoma cells." (PMID 33369441, 2020). "In glioblastoma, the research suggested that miR-708 affects glioblastoma cell proliferation, invasion, and apoptosis through regulating AKt1, CCND1, MMP2, EZH2, Parp-1 and Bcl219." (PMID 33028966, 2020). "In our investigation, we detected that AKT1 was a direct target of miR-548x and miR-4698 in glioblastoma cell lines." (PMID 32005873, 2020). "Then the expression of miR-4731, EGFR, ERK-1,2 and AKT-1,2 in two cell lines of glioblastoma (U-87MG and U-251MG) were evaluated by real-time PCR and compared with the glioblastoma cells transduced with the scramble vector as the control." (PMID 33369441, 2020). "The superior invasive capability of glioblastoma cells with high p-AKT1/ENTPD5 levels was limited when AKT1 was blocked." (PMID 31062076, 2019). "We showed that glioblastoma cells with high p-AKT1/ENTPD5 levels produced SPARC in response to acute RhoA activation." (PMID 31062076, 2019). "In glioblastoma cells, Akt1 promoted HIF1α translation in a manner that is insensitive to rapamycin or mTOR depletion." (PMID 31817676, 2019). "AKT1 is a downstream serine-threonine kinase in the RTK/PTEN/PI3K pathway which is highly activated in the majority of human glioblastomas." (PMID 29465400, 2018). "AKT1 is occasionally amplified in human malignancies, including glioblastoma and a single case of human gastric adenocarcinoma." (PMID 28082369, 2017). "The constitutive expression of human AKT1 together with zebrafish Smoothened (Smoa1), an oncogene involved in Shh signaling, led to glioblastoma-like tumors in the brain, retina and spinal cord." (PMID 28930163, 2017).
glioblastoma (continued). "MiR-451 was found to directly impact glioblastoma cell proliferation, invasion, and apoptosis by down regulating the expression of Akt1, CyclinD1, MMP-2, MMP-9 and B-Cell CLL/lymphoma 2 (Bcl-2), however, no direct interaction of any of these mRNAs were found." (PMID 24670365, 2014). "Furthermore, miR‐149 inhibited AKT1 expression and reduced the proliferative capacity of the glioblastoma multiforme U87MG cell line." (PMID 39162596, 2024). "Among glioblastoma patients, 38% harbor an alteration in one or more PI3K pathway components, most commonly PTEN loss (approximately 30% of patients), followed by mutations in PIK3CA (13%), or AKT1 (1%)." (PMID 38319732, 2024). "Firstly, we validated the interaction of TRAF4 and SETDB1 with AKT1 in glioblastoma cells." (PMID 36077559, 2022). "The circ-CFH/miR-149/AKT1 axis has the potential to be a therapeutic target for glioblastoma." (PMID 35883576, 2022). "AKT1 is an isoform of AKT, and amplification of Akt1 occurs at a higher rate in various cancers, such as gastric, breast, colon, esophageal, ovarian, pancreatic, and thyroid cancers and glioblastoma." (PMID 35590327, 2022). "The alkaloid voacangine inhibits vascular endothelial growth factor receptor 2 (VEGFR2) preventing growth of glioblastoma; The affinity of voacangine with proteins such as AKT1 (−9.0 kcal/mol) and eNOS3 (−9.1 kcal/mol) can influence downstream the VEGFR2 signaling cascade." (PMID 34205626, 2021). "In contrast, glioblastoma cells with low p-AKT1 levels had low ENTPD5 levels, which could be increased by overexpressing AKT1." (PMID 31062076, 2019). "Similarly, glioblastoma cells with low p-AKT1/ENTPD5, and thus low endogenous SPARC production, showed increased invasion through myelinated transwells in the presence of recombinant SPARC but not SPARC (del_Kazal)." (PMID 31062076, 2019). "In comparison, the white-matter invasion of glioblastoma cells with low p-AKT1/ENTPD5 levels, such as LNT229 cells, was restricted but could be improved by silencing PTEN (shPTEN)." (PMID 31062076, 2019). "The interaction between miR-149-5p and AKT1 is also reported in colon carcinoma and glioblastoma." (PMID 30717751, 2019). "Through these experiments, we demonstrated for the first time that HAX-1 could regulate cell proliferation and apoptosis of glioblastoma cells by affecting the activation of the Akt1 signal pathway via interaction with Hsp90." (PMID 29311840, 2017). "However, many studies have shown that AKT1 plays an important role in glioblastoma." (PMID 38911393, 2024). "However, not all PTEN-positive glioblastoma cells had low p-AKT1/ENTPD5 levels, whereas WT PTEN-expression in LNT229 glioblastoma cells was responsible for their low p-AKT1/ENTPD5 levels; LN18 cells retained high p-AKT1/ENTPD5 levels even in the presence of WT PTEN [Suppl." (PMID 31062076, 2019). "At this point, present findings show that 10 as anti-tumoral agent or suppressor with a good biosafety level is interrelated to proliferation and invasion of glioblastoma cells by inhibiting AKT1 signaling and 10 may be considered as an effective therapeutic treatment against glioblastoma." (PMID 29890617, 2018). "Based on the results of the PPI network and KEGG enrichment analysis, AKT1, HIF1A, CDH1, and NFKB1 were identified as vortioxetine targets that also regulate glioblastoma." (PMID 40312983, 2025). "While many genes get high EGIS in specific cancer types, such as HSP90AA1 in pancreatic cancer, AKT1 in glioblastoma and pancreatic cancer, and ACTB in glioblastoma and liver cancer." (PMID 40478912, 2025).
glioblastoma (continued). "In conclusion, the findings of the present study identified miR-4731 reduces EGFR, AKT-1,2 and ERK-1,2 expression in glioblastoma cell lines and induce cell cycle arrest and inhibit cell growth in these cells." (PMID 33369441, 2020). "On one hand, knocking-down OCT4 in embryonal carcinoma cells increased the levels of AKT1 mRNA, pAKT-T308 and pAKT-S47317, and reversely, inhibiting the PI3K/AKT pathway increased OCT4 expression in glioblastoma CSCs32." (PMID 28383051, 2017). "FOXO1 and AKT1, along with MDM2 (another common intermediary gene in the PIN) have previously been identified in differential co-expression studies of glioblastoma." (PMID 28957313, 2017). "The role of miR-149 was explored in glioblastoma where it was found to inhibit the expression of MMP-2, p-AKT1, proliferating cell nuclear antigen (PCNA), cyclin D1, as well as proliferation and invasion in U251 cells." (PMID 24670365, 2014). "Also, there is evidence that hsa-miR-181a-5p downregulates the expression of AKT1, a signaling factor of the MAPK pathway, in glioblastoma cells." (PMID 39574474, 2024). "Regarding the first signature network component, hsa-mir-137, hsa-mir-330, hsa-mir-149, hsa-mir-107, hsa-mir-181b were among the miRNAs whose experimentally validated targets (such as CTBP1, CDC42, CDK6, E2F1, VEGFA, AKT1, KAT2B) affect the pathways which play a crucial role in glioblastoma biology." (PMID 28045122, 2017). "Our bioinformatics studies by Targetscan 7.1 and miRwalk 2.0 site have predicted that miR-548x and miR-4698 could simultaneously target 3ʹUTR of PI3KCB, PI3KCA, PDK1, AKT1, mTOR, MDM2, Rheb, and CREB1 genes that some of them were upregulated in glioblastoma sample according TCGA deta." (PMID 32005873, 2020). "According to our bioinformatics studies in the TargetScan 7.1 and miRwalk 2.0 database, we predicted that some miRNAs, as well as miR-548x and miR-4698 could target some genes that are overactive in the PI3K/AKT pathway (PI3KCB, PI3KCA, PDK1, AKT1, Rheb, MDM2, mTOR, and CREB1) in glioblastoma." (PMID 32005873, 2020). "In the cell death pathway, EGF treatment induces apoptosis via AKT1 inhibition in EGFR overexpressed dominant-negative Ras mutant cell lines, or via phosphorylation of STAT3 in glioblastoma; however, the mechanisms for these pathways are not clear." (PMID 38789573, 2024). "In glioblastoma, AKT2 and AKT3 but not AKT1 promote tumor progression, and alterations in the polarity of the PH domain and the regulatory domain were identified as responsible mechanisms for the isoform-specific effect." (PMID 33670586, 2021).
colon carcinoma (313 papers, 2008 to 2026). "For MAC, patients with right-sided colon tumors had more AKT1 mutations than patients with left-sided colon tumors or patients with rectal tumors." (PMID 33738258, 2021). "For MAC, right-sided colon cancer was associated with more microsatellite instability-high tumors and more AKT1 mutations than left-sided colon cancer and rectal cancer." (PMID 33738258, 2021). "A somatic mutation affecting residue E17 of the AKT1 gene has recently been identified in breast and colon cancer." (PMID 19461960, 2009). "The AKT1-E17K mutation was initially identified as a SNP, rs34409589, but in a recent publication it was found to be a somatic mutation and was found in 3 of 51 colon cancers." (PMID 20233444, 2010). "The PPI network, visualized through the STRING database, identified key targets such as AKT1, IL6, and HSP90AA1, which are implicated in colon cancer development." (PMID 41011246, 2025). "Expression levels of Pcna, Ccnd1(CyclinD1), Bcl2, Itga2, Itgb1, Fak, Pik3r1, Akt1, Mtor and Myc were remarkably upregulated and Bax was downregulated in colonic tumors of mice treated with S. moorei." (PMID 39990665, 2025). "For instance, we have found NSC49L to be effective against colon cancer through the activation of PP2Ac and subsequently decreasing the AKT1/mTOR/4E-BP1 axis and p21 translation in FOLFOX-resistant colon cancer cells." (PMID 38184584, 2024). "For example, the inhibition of liver metastasis in colon cancer is significantly observed upon suppression of the oncogene AKT1." (PMID 38430268, 2024). "Taken together, these results suggest that AKT1 is a direct target of miR-143-3p in prostate cells, as others had shown in bladder cancer and colon cancer cells." (PMID 37759434, 2023). "For example, it has been reported that AKT1 inhibition reduced oxidative stress in cardiomyopathy rat models and colon cancer cells; meanwhile, we found in another report that LPS regulated NF-κB through a ROS-independent mechanism in J774.1 cells." (PMID 36144632, 2022). "Actually, AKT1 can act as an important regulator of EMT colon cancer cells and be a possible therapeutic target for colon cancer." (PMID 36142147, 2022). "SIRT6 can not only upregulate the expression of tumor suppressors phosphatase and tensin (PTEN), and phosphatidylinositol-4,5-biphosphate (PIP2), but also can downregulate AKT1, mTOR, cyclin D1, and c-myc to inhibit the progression of colon cancer." (PMID 35172823, 2022). "In right-sided colon tumors, patients with MAC had fewer PIK3CA mutations and more AKT1 mutations than patients with NMAC." (PMID 33738258, 2021). "To examine the cellular significance of the D44G/V45P/D46G triple mutation, we transfected the full-length Akt triple mutant into an Akt1/Akt2 knockout HCT116 human colon cancer cell line." (PMID 32744507, 2020). "Single knockdown of Akt1 and Akt2 leads to a decrease in Rad51 foci formation and significantly reduces Rad51 protein level in colon cancer cells." (PMID 32711558, 2020). "For example, AKT1 (AKT serine/threonine kinase 1) has been demonstrated to play crucial roles in the development, progression, and drug resistance of colon cancer." (PMID 33273919, 2020). "In this context, it is interesting that the results presented here for colon carcinoma HCT116 demonstrate a significantly stronger impact of Akt2 on homologous recombination repair of DSBs than that of Akt1." (PMID 31847370, 2019). "The number of migrated and invaded cells in the si-AKT1-control group was also significantly lower than that in the NC-control group (all, P < 0.001), indicating that AKT1 knockdown also reduced the migration and invasion potential of colon cancer cells." (PMID 31772677, 2019).
colon carcinoma (continued). "The inhibitory effects of JSD on colon cancer liver metastasis can be significantly weakened or even completely abrogated with AKT1 knockdown, while obviously enhanced with AKT1 overexpression (P<0.05)." (PMID 31772677, 2019). "The inhibitory effects of JSD on liver metastasis of colon cancer cells was significantly weakened when AKT1 was knocked down, while enhanced with overexpression of AKT1 (P<0.001)." (PMID 31772677, 2019). "In agreement with this study, we demonstrate here significantly reduced Rad51 foci formation when AKT1 as well as AKT2 isoforms were downregulated alone or in combination with HCT116 colon cancer cells." (PMID 31847370, 2019). "A similar situation was observed for Akt1 phosphorylation in insulin-treated HCT116 colon cancer cells." (PMID 26945062, 2016). "Recently, the inflammatory factor S100A8 was found to activate the Akt1-Smad5-Id3 axis, which promoted the proliferation, invasion and metastasis of colon cancer cells." (PMID 27177089, 2016). "The phosphorylation level of AKT1 at Thr 308 was significantly diminished after knockdown of SMYD3 in the human colon cancer SW480 cells." (PMID 27626683, 2016). "In contrast, p-Akt1 expression in Hes1-expressed colon cancer cells was observed to increase significantly in comparison with that in the control cells." (PMID 26452029, 2015). "We have further verified this interaction, with flow cytometry, western blot and mRNA expression analysis in the colon cancer cell-line DLD-1 by showing that knock-out of AKT1, AKT2 or both AKT1 and AKT2 increased the expression of CD44." (PMID 24760019, 2014). "While most of the specific amino acid mutations mirror what is seen on the COSMIC database, some unique colon cancer gene mutations were found, which include ABL1-F359V, AKT1-E17K, MET-R970C, and MET-T992I." (PMID 20233444, 2010). "In colon cancer cells, activation of AKT1 and AKT3 results in the abnormal suppression of miR-125b-5p, which subsequently leads to the upregulation of GLUT5 expression, causing metastasis and drug resistance in colon cancer cells." (PMID 41584038, 2026). "Thus, there is an increase in E cadherin expression and a decrease of N cadherin, phospho (p)-AKT1, p-GSK3β, and Snail in colon cancer." (PMID 37108477, 2023). "Their results showed that resveratrol and AKT1 knockdown treatment significantly inhibited colon cancer cell migration and invasion, increasing E-cadherin expression while decreasing that of N-cadherin, phospho (p)AKT1, pGSK3β, and Snail both in vitro and in vivo." (PMID 36829966, 2023). "Our results implied that EGLP might promote colon cancer cells apoptosis via the regulation of p-Akt1/P-ERK and Bax/Bcl-2 protein expression." (PMID 32495637, 2020). "Therefore, we concluded that the JSD-induced inhibition effects on colon cancer liver metastasis were realized by AKT1/GSK-3β signaling activation." (PMID 31772677, 2019). "The difference between the oe-AKT1-control and oe-AKT1-JSD groups was larger than that between the NC-control and NC-JSD groups (both, P < 0.001), suggesting that the ability of JSD to inhibit the healing ability of colon cancer cells was enhanced after AKT1 overexpression." (PMID 31772677, 2019). "Additionally, JSD-induced reversion of colon cancer EMT can be significantly weakened with knockdown of AKT1 and enhanced with overexpression of AKT1." (PMID 31772677, 2019). "Therefore, it can be concluded that JSD-induced reversion of EMT in colon cancer is realized by the activation of AKT1/GSK-3β signaling." (PMID 31772677, 2019). "The 24 h migration distance of cells in the si-AKT1-control group was also significantly shorter than that in cells of the NC-control group (both, P < 0.001), indicating that knockdown of AKT1 was also sufficient to inhibit the healing ability of colon cancer cells." (PMID 31772677, 2019).